NFE2L2 (NFE2 like bZIP transcription factor 2)
Diseases named in the same sentence as NFE2L2 in open-access papers (continued):
Sharing a sentence is not in itself a finding about the gene and the disease.
lung carcinoma (continued). "The results suggest that the NFE2L2-mediated genes are involved in human lung cancer pathology." (PMID 26596768, 2015). "We have previously reported the somatic mutations of the NRF2 gene (NFE2L2), however, the correlation between the Keap1 mutation and the clinicopathological features of lung cancer has not been well investigated." (PMID 24137397, 2013). "Thus, NFE2L2 may inhibit ferroptosis in lung cancer cells mainly through increased AIFM2/FSP1 expression." (PMID 39025451, 2024). "YEATS4 amplification samples show increased mRNA levels of several well-known antioxidant genes, including NQO1, SLC7A11, and GCLC, suggesting beside NFE2L2 mutation and KEAP1 mutation, YEATS4 amplification could be the other critical genetic marker in lung cancer by modulating antioxidant pathways." (PMID 38514704, 2024). "Thus, these genes are mutated in 10–30% of lung cancer, whereas no mutations have been found in NFE2L2 or KEAP1 in pancreatic cancer." (PMID 37373496, 2023). "NFE2L2 activity is further enhanced by serine/threonine kinase 11 (STK11) and KEAP1 co-mutation, which induces expression of ferroptosis-protective genes, such as stearoyl-CoA desaturase (SCD) and aldo-keto reductase 1 C family 1/2/3 (AKR1C1/2/3) in lung cancer cells." (PMID 34742351, 2021). "Moreover, NFE2L2 is abnormally overexpressed in lung cancer cell line A549." (PMID 33101586, 2020). "We found that an NFE2L2-mediated gene signature could effectively predict lung cancer survival." (PMID 26596768, 2015). "NFE2L2 is positively regulated in two sets of lung cancer data, one set of leukemia, and in the PAH set, and negatively regulated in three sets of lung cancer, two of breast cancer, and in one of leukemia." (PMID 36101460, 2022). "The expression of NFE2L2 is also regulated by ubiquitin specific peptidase 11 (USP11) and activating transcription factor 2 (ATF2) in lung cancer cells." (PMID 34742351, 2021). "The overexpression of nuclear Nrf2 and the subsequent increase in the antioxidant defense in lung cancer cells are mainly related to genetic and epigenetic alterations of the KEAP1 and NFE2L2 genes." (PMID 27847554, 2016). "The results indicate that DeepCellEss predicts NFE2L2 to be essential in two types of lung cancers but non-essential in non-cancerous, implying that our essentiality predictor is useful for IDPs and has the potential to find some cancer-related essential IDPs." (PMID 36458923, 2023). "Despite the well-documented impact of KEAP1 and NFE2L2 mutations in NSCLCs and LCNEC, the prognostic role of KEAP1 methylation in lung cancer has not yet been clarified." (PMID 31159323, 2019). "Inferred TF activity of NFE2L2 was increased in mutant versus WT KEAP1 or NFE2L2 lung cancers; these differences are not observed at the gene expression level." (PMID 28139702, 2017). "In the lung cancer group, PRKG2 exhibited significant positive correlation with NFE2L2, SLC40A1, TFRC, and significant negative correlation with CHAC1 and HSPB1." (PMID 39744538, 2024).
breast cancer (67 papers, 2015 to 2026). A primary or metastatic malignant neoplasm involving the breast. "Conversely, lower NFE2L2 levels have been associated with poorer prognosis, particularly in luminal breast cancer, which is consistent with our findings." (PMID 39767718, 2024). "In agreement with our results, previous studies have reported that the compensatory activation of autophagy was induced in breast carcinoma cells and cardiomyocytes and was associated with p62-related NFE2L2 activation and inhibition of proteasome activity." (PMID 33364966, 2020). "To shed some light on this paradox, we analysed the NFE2L2 mRNA expression levels in breast cancer and its association with clinicopathological features and survival." (PMID 27770790, 2016). "In summary, in our data we identified a predictive potential of NFE2L2 mRNA expression levels in breast cancer, especially in ER positive breast cancer, since high NFE2L2 expression was associated with better survival." (PMID 27770790, 2016). "However, coexpression of high levels of both PTGS2 and NFE2L2 was found to be significantly associated with the increased survival rate in breast cancer patients (p < 0.05)." (PMID 33801351, 2021). "Reduced expression of NFE2L2 are associated with poor outcome in breast cancer, ovarian cancer, and prostate cancer, but with favorable prognosis in cervical cancer, adrenocortical carcinoma, and kidney renal clear cell carcinoma, highlighting the dual role of NFE2L2 in cancer." (PMID 34422643, 2021). "Although its role in breast cancer progression remains controversial, some studies suggest that high NFE2L2 levels enhance antioxidant responses, promoting chemoresistance and metastasis." (PMID 39767718, 2024). "Recent research indicated that reduced expression of NFE2L2 was related to a better prognosis of breast cancer." (PMID 37874682, 2023). "For clinical validation we evaluated tumor samples of breast cancer patients for an upregulation of NRF2 and NFE2L2, the gene encoding for NRF2, as reaction to tamoxifen treatment." (PMID 36755288, 2023). "Breast cancer patients with high NFE2L2 expression had a lower RFS rate than those with low NFE2L2 expression (p < 0.001)." (PMID 35017469, 2022). "We compared NFE2L2 mRNA expression levels between cancerous and the respective normal breast tissues from a subgroup of 108 breast cancer patients of the TCGA dataset." (PMID 27770790, 2016). "In the current study we identified a significant beneficial role of elevated NFE2L2 mRNA expression levels in the tumour for the survival of breast cancer patients based on two independent cohorts in agreement with NFE2L2 acting as a tumour suppressor." (PMID 27770790, 2016). "In the training cohort we identified the 65th percentile regarding NFE2L2 mRNA expression levels as an optimal cut-off value to discriminate between breast cancer patients with a better DSS and those with a poorer outcome." (PMID 27770790, 2016). "The comparison of paired normal and cancerous breast tissues from 108 breast cancer patients identified a higher NFE2L2 mRNA expression in normal tissues, what underscores its role as a tumour suppressor." (PMID 27770790, 2016). "Since the NFE2L2 pathway was recently shown to be more active in steroid receptor positive breast cancer, we focused on ER status." (PMID 27770790, 2016). "We retrospectively evaluated the NFE2L2 mRNA expression levels in tumour tissue of two independent breast cancer patient cohorts." (PMID 27770790, 2016). "In the present study we investigated the predictive role of NFE2L2 mRNA expression levels in breast cancer patients of two independent cohorts." (PMID 27770790, 2016). "We concluded that reduced NFE2L2 mRNA expression in tumour tissues is an independent predictor of shortened survival in breast cancer patients." (PMID 27770790, 2016). "Moreover, the NFE2L2 gene is overexpressed in many types of human tumors, such as breast cancer or gastric cancer, which contributes to chemoresistance." (PMID 35056649, 2022).
breast cancer (continued). "However, our analysis did not identify a number of known mutational cancer drivers, for example, CTNNB1 in hepatocellular carcinoma, PIK3CA in breast cancer and NFE2L2 in lung squamous cell carcinoma." (PMID 34313788, 2021). "Taken together, these findings indicate that the expression of PTGS2, NFE2L2, and HMOX1 correlates with poor clinical outcomes and may be exploited as diagnostic and/or therapeutic targets in breast cancer." (PMID 33801351, 2021). "Univariate survival analysis of all 176 breast cancer patients composing the test set using the 65th percentile as cut-off revealed that breast cancer patients with high NFE2L2 mRNA expression levels had a better RFS (P = 0.013) in comparison to those with low NFE2L2 mRNA expression levels." (PMID 27770790, 2016). "It was not analysed within this study if the downregulation of NFE2L2 mRNA expression in breast cancer is related to oncogenic NFE2L2 mutations." (PMID 27770790, 2016). "Interestingly, another study describes a correlation between a more active NFE2L2 pathway and a more favourable outcome in ER/PR positive breast cancer compared to triple negative breast cancer, similar to our results found in the ER positive subgroup of breast cancer patients." (PMID 27770790, 2016). "Six ferroptosis-related genes (SLC7A11, GPX4, FTH1, NQO1, NFE2L2, SQSTM1) demonstrated consistent upregulation across all breast cancer subtypes, with higher expression observed in more aggressive tumors." (PMID 42074090, 2026). "In fact, our data suggest that reduced NFE2L2 mRNA levels correlate with a worse response to treatment in terms of pCR and RFS in luminal breast cancer." (PMID 39767718, 2024). "Since either PHA treatment or Baf A1/PHA cotreatments induced ROS, the effects of autophagy in antioxidant gene expressions such as SOD1, NFE2L2, TXN, and GSR in breast cancer cells were assessed by real-time PCR." (PMID 35883843, 2022). "Previous studies have reported that NFE2L2 is highly expressed in GC and has anti-inflammatory and antioxidant effects, while DLST has been studied in neuroblastoma, breast cancer, and other tumor diseases, and GC-related studies are rare." (PMID 36249422, 2022). "The combination of quercetin and vitamin C decreased the expression of NFE2L2 in both the mRNA and protein levels in the MDA-MB 231, MCF-7, A549, and MDA-MB 468 breast cancer cell lines." (PMID 35056649, 2022). "Thus, different breast cancer subtypes may have different molecular environments, including oxidative stress sensitivity and ROS-dependent regulation of the stress response transcription factor, NFE2L2, which is related to estrogen response." (PMID 35805595, 2022). "Thus, determination of the NFE2L2 mRNA expression level might be clinically useful to improve the characterization of breast cancer, eventually leading to more efficient and personalized treatment of breast cancer patients." (PMID 27770790, 2016). "Therefore we assume that NFE2L2 mutations do not play a major role in breast cancer." (PMID 27770790, 2016). "We identified networks regulated by known cancer drivers such as GATA3 and FOXA1 (breast cancer), SOX17 and FOXA2 (endometrial cancer), and NFE2L2, SOX2, and TP63 (squamous cell lung cancer)." (PMID 25994056, 2015). "The results revealed that breast cancer tissues exhibited lower expression levels of SAT1, ALOX5, ALOX12, ATF3, ATF4, GPX4 and NFE2L2 compared to normal tissues; conversely, higher expression levels of ALOX15, ALOXE3 and HO‐1 were observed in breast cancer tissues than in normal tissues." (PMID 38516826, 2024). "Finally, through in silico studies, we identified specific biomarkers, including TOMM20, NFE2L2, CAT, and ESR2, correlated with poor prognosis in luminal breast cancer." (PMID 39767718, 2024). "Moreover, high expression of all three genes (PTGS2, NFE2L2, and HMOX1) correlated with poor prognosis in breast cancer patients." (PMID 33801351, 2021).
breast cancer (continued). "In non-SCC breast cancer, TrkB kinase activity has been shown to reduce levels of the Keap inhibitor, which increases Nfe2l2 directed transcription." (PMID 31221127, 2019). "Another recently reported link between EMT and NFE2L2 signalling is the upregulation of the HIF-1α-NOTCH axis seen after the knockdown of KEAP1 and overexpression of NFE2L2, these changes were reported to promote EMT-derived breast cancer cell migration." (PMID 31752195, 2019). "Univariate survival analysis of all 1942 breast cancer patients revealed that patients with high NFE2L2 mRNA expression levels had a better DSS (P = 0.005) and OS (P = 0.003) in comparison to those with low NFE2L2 mRNA expression levels." (PMID 27770790, 2016). "Furthermore, high expression of NFE2L2 is positively correlated with the number of tumor-infiltrating lymphocytes, expression of immune checkpoint molecules and TME in the ER-Positive/HER2-Negative breast cancer." (PMID 37794491, 2023). "In addition, DHA was also reported as inducing the expression and nuclear translocation of the oxidative stress sensitive transcription factor, NFE2L2/Nrf2, and to increase the expression of oxidative stress-induced growth inhibitor 1 (OSGIN1) in MCF-7 and Hs578T breast cancer cells." (PMID 35805595, 2022). "In conclusion, our findings indicate that markers including ESR2, TOMM20, NFE2L2, and CAT not only play a role in mitochondrial oxidative stress but may also influence drug response and cancer recurrence, making them promising biomarkers to predict prognosis in luminal breast cancer." (PMID 39767718, 2024).
diabetes (54 papers, 2013 to 2026). "Comparatively, NFE2L2 had pivotal roles in many signaling pathways that were altered in the retina in diabetes, and were implicated in the development of DR." (PMID 38243268, 2024). "The association between the interaction of KEAP1 and NFE2L2 has been implicated in the pathogenesis of various chronic conditions, such as diabetes, cancer, and neurodegenerative illnesses." (PMID 37794491, 2023). "It is interesting that NFE2L2 SNPs are also associated with diabetes mellitus, which is one of most common comorbidities of TB." (PMID 34108963, 2021). "However, it remains unknown whether NFE2L2 polymorphisms are associated with the risk of diabetes and diabetic complications." (PMID 27374075, 2016). "Conversely, Nfe2l2 showed significantly elevated expression across the same branch, implying a potential compensatory or stress responsive transcriptional shift in diabetes." (PMID 41397560, 2026). "Nuclear factor E2-related factor 2 (NRF2) is encoded by the NFE2L2 gene, and the NRF2/ARE signaling pathway is considered a potential therapeutic strategy for antioxidative stress-mediated diseases, such as diabetes, fibrosis, and cancer." (PMID 36105099, 2022). "Regarding pancreatic β cells dysfunction in diabetes, emerging evidence suggests that NFE2L2-mediated ferroptosis plays a crucial role in β-cell function." (PMID 35992146, 2022). "Similar observations have been reported in other organisms and these findings suggest that Nfe2l2 increases as the initial response to oxidative stress in diabetes to overcome injury." (PMID 35294499, 2022). "Reportedly, Nfe2l2 significantly increases in the kidney after three months of diabetes, followed by a significant reduction at six months, indicating initial upregulation." (PMID 35294499, 2022). "On the other hand, rosiglitazone can not only activate NFE2L2 to protect cells from oxidative stress, but also play an important role in the prevention and treatment of diabetes and its complications." (PMID 30521536, 2018). "The transcription factor nuclear factor erythroid 2‐like 2 (NFE2L2) is essential for preventing type 2 diabetes mellitus (T2DM)‐induced complications in animal models." (PMID 27374075, 2016). "However, previous work has identified key roles for NRF2 in beta cell proliferation and polymorphisms in NFE2L2, the NRF2-encoding gene, and pathway have been associated with diabetes risk." (PMID 38479223, 2024). "In the non-cancerous cellular domain, NFE2L2 gene variants affect metabolic and renal function parameters in patients with diabetes and hypertension; are also genetic markers of susceptibility to cirrhosis; and evidence has even been found in the effect of obesity on heart rate." (PMID 37060021, 2023). "Therefore, NFE2L2 dysfunction might serve as the common mechanism leading to TB and other diseases such as diabetes mellitus." (PMID 34108963, 2021). "Compared with the normal control group, the mRNA levels of NLRP3, NFE2L2, and NFKB1 in the diabetes model group were significantly increased, while they decreased in the SAL treatment group (P < 0.05), with the statistical difference." (PMID 38243268, 2024). "The hyperinsulinaemic glucose clamp technique was used to induce equivalent hypoglycaemia and to control post-hypoglycaemic glucose levels in mice with and without STZ-diabetes and Nrf2−/− mice (lacking Nrf2 [also known as Nfe2l2])." (PMID 37015997, 2023). "We further found that NaB improved the diabetes‐induced aortic endothelial dysfunction in the wild‐type, but not Nfe2l2 gene knockout, mice." (PMID 32628815, 2020).